INS (insulin)
Diseases named in the same sentence as INS in open-access papers (continued):
Sharing a sentence is not in itself a finding about the gene and the disease.
corneal diseases (3 papers, 2021 to 2024). "This review systematically evaluates the efficacy of topical insulin across different corneal disorders." (PMID 38989397, 2024). "Overall, the comprehensive review highlights the potential of topical insulin as a novel therapeutic approach in corneal diseases, paving the way for future research and clinical applications." (PMID 38989397, 2024). "This study was a systematic review of all currently published case reports, case series, clinical studies, and clinical trials, regarding the use of topical insulin in corneal diseases." (PMID 38989397, 2024). "On the other hand, the sex, T2DM-related complications and T2DM medications including DPP4 inhibitors and insulin did not alter the correlation between SGLT2 inhibitors application and the development of corneal diseases." (PMID 38322591, 2024). "Besides, the T2DM duration and T2DM medications that could reflect the glycemic levels such as DPP4 inhibitors and insulin did not alter the effect of SGLT2 inhibitors on corneal diseases development, which further support the universal protective effect of SGLT2 inhibitors on corneal disorders." (PMID 38322591, 2024).
craniopharyngioma (3 papers, 2009 to 2011). A benign, partly cystic, epithelial tumor of the sellar region, presumably derived from Rathke pouch epithelium. "The outcome of this pilot study is encouraging and does provide necessary data for a larger randomized trial in individuals with hypothalamic obesity including children with craniopharyngioma and others who exhibit hypersecretion of insulin." (PMID 21603206, 2011). "We have shown that the pre-surgery plasma fasting insulin concentrations of children with craniopharyngioma are positively correlated with the weight change (kg) during the year after surgery." (PMID 19341477, 2009). "Furthermore, in craniopharyngioma survivors it has been identified a difference in insulin sensitivity that was found lower if analyzed by Frequently Sampled Intravenous Glucose Tolerance Test (FSIGT) rather than by Oral Glucose Tolerance Test (OGTT)." (PMID 21846381, 2011). "Exaggerated GLP-1 secretion in response to an oral glucose load in individuals treated for craniopharyngioma might link the findings of insulin secretion and autonomic dysregulation." (PMID 21846381, 2011). "In this study, a novel therapeutic approach based on combined treatment both to decrease insulin secretion using diazoxide and at the same time enhancing insulin action through the use of metformin was utilized to treat children with hypothalamic obesity secondary to craniopharyngioma surgery." (PMID 21603206, 2011).
cryptorchidism (3 papers, 2015 to 2024). The failure of one or both testes of a male fetus to descend from the abdomen into the scrotum during the late part of pregnancy. "Whether down regulated expression of DHH or increased insulin levels in umbilical cord blood can cause cryptorchidism in newborn males is unclear." (PMID 25798927, 2015). "In this study, the differentially expressed proteins (DEPs) found in the seminal plasma of giant pandas with cryptorchidism, compared to those with normal testes, showed a marked enrichment in the insulin signaling pathway." (PMID 39457412, 2024). "Furthermore, bioinformatics analysis showed that these identified DEPs played an important role in insulin signaling, affecting the defects of cryptorchidism and semen quality." (PMID 39457412, 2024).
DEND syndrome (3 papers, 2012 to 2024). DEND syndrome is a very rare, generally severe form of neonatal diabetes mellitus (NDM) characterized by a triad of developmental delay, epilepsy, and neonatal diabetes. "The patient with DEND syndrome was initially misdiagnosed as having type 1 DM; however, insulin therapy was successfully switched to oral sulfonylurea therapy." (PMID 33663443, 2021).
dengue (3 papers, 2015 to 2020). "To determine whether the Ras/ERK pathway is involved in the anti-dengue response in mosquito cells, we use human insulin as an agonist of ERK signaling since it promotes ERK phosphorylation in insect cells." (PMID 32866199, 2020). "Insulin infusion rate was also tailed off according to the sugar level; we did not administer intravenous dextrose as it might have worsened the plasma leak from the dengue fever." (PMID 29078811, 2017). "After 2 days of recovering from the critical phase of dengue fever, his blood sugars were within normal limits without insulin, and his urine ketone bodies were persistently negative." (PMID 29078811, 2017).
dysplasia (3 papers, 2018 to 2021). A usually neoplastic transformation of the cell, associated with altered architectural tissue patterns. "The analysis of the trend across mice that developed dysplasia was performed across three group (MKR males did not develop dysplasia) and showed, in parallel with the healthy mice, increased insulin (Cuzick z = +3.51, p = 4 × 10−4) and C-peptide serum levels (Cuzick z = +3.28, p = 0.001)." (PMID 29662006, 2018).
echinococcosis (3 papers, 2014 to 2022). A parasitic infection caused by tapeworm larvae of Echinococcus. "By our investigations on the inhibition of insulin signalling pathways in E. multilocularis, we also identified a lead compound that could facilitate the development of novel and effective anti-echinococcosis drugs in the future." (PMID 24468049, 2014). "In addition, miR-184 may regulate the function of pancreatic beta-cells through glucose metabolism, alter insulin secretion, and thus down-regulate the GDF3 gene, leading to the final infection of hydatidosis in canine." (PMID 32596042, 2020).
endometrioid adenocarcinoma (3 papers, 2013 to 2024). An adenocarcinoma characterized by the presence of malignant glandular epithelial cells resembling endometrial cells. "There is also clear evidence showing a positive association between the increased levels of circulating insulin and the incidence of endometrioid adenocarcinoma." (PMID 24308813, 2013). "Eight common proteins were identified between normal endometrium with diploid endometrioid carcinomas and diploid with aneuploid endometrioid carcinomas, namely ACTB, ATP5B, ATP5E, INS, IVNS1ABP, LMNB, PLS1, and VIM." (PMID 39194522, 2024).
endometritis (3 papers, 2013 to 2025). An acute or chronic, usually bacterial infectious process affecting the endometrium. "It has been reported that infections affect insulin signal transduction and metabolic endocrine control, and in rats with endometritis induced by Escherichia coli and Staphylococcus aureus, the activity of iNOS and the levels of NO and COX-2 are elevated." (PMID 40514455, 2025). "Severe inflammatory conditions like metritis and subclinical endometritis with intensive release of cytokines potentially further depress insulin secretion of pancreatic β-cells and whole-body insulin responsiveness in dairy cows." (PMID 24209779, 2013). "The concentration of insulin remained high in normal and subclinical endometritis cows compared to clinical endometritis and metritis cows." (PMID 24209779, 2013). "However the insulin concentration increased at 3 weeks postcalving to the level as clinical endometritis and decreased abruptly to a lower concentration at 7 weeks." (PMID 24209779, 2013). "Cows with metritis and clinical endometritis almost always had higher adipokines and lower metabolic hormone levels than subclinical endometritis and normal cows at any time-point during the study period, except for insulin and IGF-1." (PMID 24209779, 2013). "The present study demonstrated that circulating adipokines, insulin, and IGF-1 differed in cows with metritis, clinical endometritis or subclinical endometritis, in cows with persistent postpartum uterine inflammation and in cows with low versus high body condition." (PMID 24209779, 2013). "Furthermore, serum leptin, TNF-alpha, IL-1beta and IL-6 were higher in cows with subclinical endometritis compared to normal cows (P < 0.05), and insulin and IGF-1 concentrations were lower in cows with metritis or clinical endometritis." (PMID 24209779, 2013).
experimental autoimmune encephalomyelitis (3 papers, 2009 to 2019). An autoimmune demyelinating disease of the central nervous system that is produced experimentally in animals by the injection of homogenized brain or spinal cord in Freund's adjuvant. "For instance, mucosal administration of antigen during experimental autoimmune encephalomyelitis (EAE) may exacerbate inflammation and oral administration of high dose insulin may induce autoimmune diabetes." (PMID 20142990, 2009).
Failure to thrive (3 papers, 2017 to 2024). Failure to thrive (FTT) refers to a child whose physical growth is substantially below the norm. "In our series, we evaluated the growth status for a median duration of 4 years (oldest patient now 18 years old) and found that the majority of cases have failure to thrive and short stature despite treatment with replacement doses of insulin and pancreatic enzymes." (PMID 32893856, 2020). "Lack of insulin is known to lead to a hypercatabolic state illustrated by the failure to thrive." (PMID 28458655, 2017).
falciparum malaria (3 papers, 2014 to 2025). "As previously shown, plasma concentrations of βHBA are elevated in severe falciparum malaria, provided ketogenesis has not been suppressed by quinine-induced insulin secretion, and correlate well with plasma creatinine concentrations (r = 0.68, p = 0.001)." (PMID 29566677, 2018).
Follicular Cyst (3 papers, 2023 to 2025). Cyst due to the occlusion of the duct of a follicle or small gland. "The results showed that the follicular cysts were characterized by significant lower E2, insulin, IGF1 and leptin levels but elevated ACTH and ghrelin levels compared with normal follicles (p < 0.05)." (PMID 37958056, 2023). "Firstly, follicular cyst follicles had extremely significant lower E2, insulin, IGF1 and leptin levels compared with normal follicles (p < 0.01)." (PMID 37958056, 2023).
gastric disease (3 papers, 2021 to 2023). "The study of insulin-gastrin (INS-GAS) transgenic mouse model suggests that further study is needed on the role of immune regulation in preventing the progression of gastric diseases." (PMID 35444235, 2022). "For example, INS-GAS mice, a transgenic mouse line that overexpresses human gastrin and has increased indices of gastric disease, have reduced gastric disease progression and severity when maintained under germfree conditions or when treated with antibiotics under conventional housing." (PMID 36907988, 2023).
graft versus host disease (3 papers, 2012 to 2022). An immune system disorder that occurs after allogeneic hematopoietic stem cell transplant and is a reaction of donor immune cells against host tissues. "It is worth noting that GCs, often administered in high doses for the treatment of graft-versus-host disease, are well known to contribute to worsening of metabolic disturbances by promoting gluconeogenesis and lipogenesis, while increasing insulin resistance." (PMID 34298827, 2021).
hematoma (3 papers, 2017 to 2024). A hematoma is a collection of blood from a vascular structure into an extravascular space. "The change in skin color, hematoma formation, and wound closure time following the topical application of insulin can be attributed to its multifaceted effects on various cellular processes involved in wound healing." (PMID 38731363, 2024). "In total, 42 AE occurred in 17 participants during the study, 21 (50%) of which were unrelated to study procedures, for example, a cold or hematoma occurred from the participants' own insulin catheters or own CGMs worn before the start of the study." (PMID 30067410, 2018). "Regarding hematoma formation, insulin’s anti-inflammatory properties play a crucial role." (PMID 38731363, 2024). "Furthermore, insulin’s promotion of angiogenesis may facilitate the resolution of hematomas by enhancing blood vessel formation and remodeling." (PMID 38731363, 2024).
Hodgkin's disease (3 papers, 2015 to 2025). "A multiparous patient, diagnosed with Hodgkin’s lymphoma (HL), nodular sclerosis subtype, in October 2020, was already undergoing treatment for type 1 diabetes with Insulin Lispro and Glargine." (PMID 39857724, 2025).
Hyperchloremia (3 papers, 2024 to 2025). An abnormally increased chloride concentration in the blood. "Insulin and metformin usage were associated with electrolyte imbalances, with long-term use leading to hyperchloremia." (PMID 39449943, 2024). "Current DKA management protocols often use normal saline for insulin infusion, which can contribute to hyperchloremia." (PMID 40355176, 2025). "The rationale underlying our intervention included the use of more concentrated insulin to minimize the total amount of chloride and fluid in the insulin preparation to prevent hyperchloremia." (PMID 40355176, 2025). "Although the incidence of iatrogenic hyperchloremia may seem clinically insignificant, it is unclear if this led to an increased duration of time on insulin infusions and increased ICU and hospital length of stay, as demonstrated by our retrospective study." (PMID 39981474, 2025). "This suggests that larger volumes of isotonic saline used for initial resuscitation led to increased incidence of secondary hyperchloremia, non-anion gap metabolic acidosis, increased duration of insulin infusion, and increased ICU length of stay." (PMID 39981474, 2025).
Hypocholesterolemia (3 papers, 2011 to 2021). An decreased concentration of cholesterol in the blood. "As we have shown, this approach permits us to study hyper- and hypocholesterolemia simultaneously without affecting liver function, insulin levels, animal weight, or circulating steroid hormone levels." (PMID 22279565, 2012).
Hypoxemia (3 papers, 2013 to 2025). An abnormally low level of blood oxygen. "Hypoxemia and the rise in PaO2 caused by oxygen therapy are likely to influence the concentration of catecholamines in blood, which can rapidly influence the sensitivity of peripheral tissues to insulin." (PMID 33407328, 2021). "Hypoxemia may be a physiological biomarker that reflects underlying factors and mechanisms, similar to how a single morning glucose level reflects many underlying mechanisms from insulin sensitivity to muscle utilization of glucose." (PMID 40638677, 2025). "Hypoxemia is an important stimulus for increasing sympathetic activity which in turn can impair glucose homeostasis by increasing glycogen breakdown and gluconeogenesis and for releasing inflammatory factors with deleterious effects on insulin synthesis and peripheral action." (PMID 23613841, 2013).
Inguinal hernia (3 papers, 2020 to 2025). Protrusion of the contents of the abdominal cavity through the inguinal canal. "Some biological processes underlying BMI variation including impaired adipogenesis or insulin-signaling pathways may have consequences on inguinal hernia development." (PMID 37947923, 2023).
insulinsecretion (3 papers, 2001 to 2021). "These micrographs are indicative of the suppression of insulinsecretion by pentamidine being associated with marked reductions in β-cellviability, but the plasma membrane was largely intact as there was noleakage of insulin, a 5.5 kDa peptide, from the cell interior." (PMID 33857146, 2021). "The depolarizing actionsof arginine also stimulated a significant increasein SAM-induced insulin release but 2-ketoisocaproicacid (KIC) inhibited SAM induced insulinsecretion indicating a possible competition betweenthe preferential oxidative metabolism of these twoagents." (PMID 12369722, 2001).
intraepithelial neoplasia (3 papers, 2016 to 2025). A precancerous neoplastic process that affects the squamous, glandular, or transitional cell epithelium without evidence of invasion. "Importantly, these post-meal metabolic surges are not only cardiometabolic but also oncogenic triggers—fueling inflammation, insulin signaling, and epithelial dysplasia." (PMID 41235333, 2025).
keratitis (3 papers, 2022 to 2025). A corneal disease that is characterized by inflammation of the cornea. "The comparisons of OSDI score, TBUT, keratitis, Lissamine Green staining, tear secretion (ST), and IOP showed a positive trend favoring the insulin eye drops (INS) but without statistical significance." (PMID 40700082, 2025).
keratoconus (3 papers, 2014 to 2025). A degenerative, structural disorder of the eye, characterized by a cone-shaped protrusion of the cornea. "In both groups, the patients with grade 1 keratoconus had faster epithelial healing on the second postoperative day (patient 1 in the insulin group and patient 2 in the control group)." (PMID 41470103, 2025). "Corneal fibroblasts and serum-starved fibroblasts from keratoconus patients showed differential responses to insulin and TGF β1 that will be further investigated to elucidate disease-specific molecular changes." (PMID 25247416, 2014). "This study presents a case series of 8 patients with progressive keratoconus who, following CXL, received either topical insulin (1 IU/mL, dosage and mixture consistent with prior studies) or artificial tears as an adjunct therapy to standard treatment." (PMID 41470103, 2025).
lactose intolerance (3 papers, 2020 to 2024). "In humans, LAB promote health and show several beneficial effects, e.g., a reduction in lactose intolerance, maintenance of normal insulin level, antidiarrheal, antineoplastic, and anti-inflammatory activity, among others." (PMID 34574202, 2021).
legionellosis (3 papers, 2023 to 2025). Any disease caused by Legionella bacteria. "For instance, C. elegans p38 MAP kinase mutants were more, while daf-2 insulin signaling pathways mutants were less susceptible to Legionella infection." (PMID 39453963, 2024).
lentivirus infection (3 papers, 2019 to 2024). Virus diseases caused by the Lentivirus genus. "Overexpression of GAS5 by lentivirus infection increased glucose-stimulated insulin secretion and insulin content." (PMID 33195407, 2020). "To explore the role of FA2H in β cell insulin secretion, we generated FA2H knockout (FA2H KO) MIN6 cells by CRISPR/Cas9 and FA2H overexpression (FA2H OE) cells by lentivirus infection." (PMID 39442620, 2024).
limb ischemia (3 papers, 2022 to 2025). A ischemia that involves the limb. "Limb ischemia activates AMPK in muscle, and subsequent reperfusion enhances insulin-stimulated vasodilation, potentially eliciting a more pronounced exercise effect with reduced workload." (PMID 40892466, 2025). "Collectively, these findings suggest that short-term limb ischemia enhances AMPK activation in skeletal muscle during exercise, which may improve muscle insulin sensitivity in the period after exercise." (PMID 40892466, 2025).
lipidosis (3 papers, 2021 to 2024). "Problems in insulin signaling in the liver have been linked to lipidosis, as emphasized by Lake and Abasht." (PMID 38262955, 2024).
maple syrup urine disease (3 papers, 2017 to 2025). An autosomal recessive inherited disorder caused by mutations in the BCKDHA, BCKDHB, DBT, and DLD genes. "BCKD dysfunction can arise not only from genetic disorders such as maple syrup urine disease but also from factors including fatty acids, inflammatory cytokines, oxidative stress, and elevated insulin levels." (PMID 40699723, 2025). "Impaired function of the BCAT and BCKDH enzymes has been observed in genetic disorders such as maple syrup urine disease or as a result of elevated concentrations of fatty acids, proinflammatory cytokines, or insulin." (PMID 33592103, 2021).